BRCA1 (BRCA1 DNA repair associated)
Diseases named in the same sentence as BRCA1 in open-access papers (continued):
Sharing a sentence is not in itself a finding about the gene and the disease.
cancer (continued). "Collectively, these findings suggest that loss of PARP1 replication activity due to PARPi, PARP1 deletion or FANCJ loss is toxic to BRCA1 deficient cells predicting that PARPi efficacy in BRCA mutant cancer derives from loss of PARP1 S-phase activity and not PARP1 trapping." (PMID 38521768, 2024). "Once a BRCA1 or BRCA2 germline pathogenic variant has been identified in a family, testing of at-risk relatives can identify those family members who also have the familial pathogenic variant and thus need increased surveillance and specific treatments when a cancer is identified." (PMID 38509102, 2024). "However, it is important to note that the exact mechanism by which BRCA1 influences the initiation and progression of cancer tumors remains unclear." (PMID 38224491, 2024). "We hypothesized that circulating miRNAs profiles could be used to identify germline BRCA1/2 mutations among otherwise healthy individuals without cancer." (PMID 37291133, 2023). "As a result of nonsense mutations in BRCA1 and BRCA2, DSB repair cannot efficiently take place, and this results in continuous genome instability, high mutational load, chromosomal rearrangements, and overall defective genome maintenance, which results in cancer development." (PMID 38017453, 2023). "However, more than half of all carriers with BRCA1/2 mutations have no family history of cancer, which would prompt a referral for genetic testing." (PMID 37291133, 2023). "Furthermore, the allelic composition of cancer susceptibility variants in genes distinct from BRCA1/2 is generally not evaluated in healthy populations at higher risk." (PMID 36845387, 2023). "However, cancer-predisposition genes other than BRCA1/2 have not been well studied in the population of Bahrain." (PMID 37656691, 2023). "Additionally, keeping in mind that patients’ harboring BRCA1/2 or HRR mutations are benefitted from conventional PARP-1 inhibitors, PARP-1 Auger therapy has the advantage that its use can be extended beyond BRCA1/2 defective cancers." (PMID 36834491, 2023). "Although germline variants in BRCA1, BRCA2 and other HR repair (HRR) pathway genes have been described in large sequencing studies of pediatric oncology patients, the relevance of these findings to pediatric cancer pathogenesis remains unclear." (PMID 36585449, 2023). "Since the first reports of pathogenic variants in BRCA1 and BRCA2, the breast- and ovarian cancer-predisposing genes (CPGs), almost 30 years ago, it is increasingly evident that there are unlikely to be other major high-risk genes contributing to these cancers." (PMID 36833203, 2023). "In both pathogenic BRCA1 mutant cancer cells and BRCA1 siRNA depleted cancer cells, Arlt and colleagues showed that two CFSs, FRA3B and FRA16D, manifested elevated expression of the fragility compared to wild-type BRCA1 complemented or control siRNA transfected cells." (PMID 37035242, 2023). "The usage of a targeted therapy drug is context-dependent, and RNF168 inhibition may not be beneficial in all cancers with BRCA1 mutations." (PMID 37760968, 2023). "Furthermore, even in BRCA1/2-proficient cancer cells, blocking two DSB repair pathways may exploit genomic instability more efficiently and lead to cell death." (PMID 37777505, 2023). "It is worth noting that not all pathogenic BRCA1/2 variant carriers develop cancer in a lifetime." (PMID 35908255, 2023).
cancer (continued). "We did not identify any mutations which were directly homologous to the human BRCA1 and BRCA2 germline variants which have been confirmed to increase the risk of cancer in humans, however we did find variants which potentially could influence the function of the BRCA1 and BRCA2 proteins." (PMID 36635367, 2023). "In addition, non-cancerous cells replicate slower than cancer cells, lack BRCA1 mutations and maintain homologous repair capabilities, which allows them to survive in the presence of PARP inhibitors." (PMID 37156759, 2023). "However, the rise of BMX may also be due to the dissemination and increased use of sensitive diagnostic tests such as magnetic resonance imaging (MRI), and genetic testing for BRCA1 and BRCA2 (BRCA1/2) and other mutations that tangibly affect cancer risk." (PMID 37083300, 2023). "Therefore, the cancer risks in relatives of BRCA1/2 carriers in Chinese women might be different from Caucasian women." (PMID 36861435, 2023). "Finally, the combined treatment of PARPi and immunotherapy agents may further improve the efficacy of PARPi and renders a more hopeful perspective for the BRCA1/2 mutant cancer patients." (PMID 37035242, 2023). "Female relatives of BRCA1 carriers had significantly higher risks for ovarian (RR = 4.72, 95% CI = 2.16-10.31; P < 0.001), liver (RR = 6.30, 95% CI = 1.35-29.36; P = 0.016), and any cancers (RR = 1.22, 95% CI = 1.02-1.46; P = 0.032) than female relatives of BRCA2 carriers." (PMID 36861435, 2023). "No known inactivating mutations in DDR genes were observed in patients’ biopsy samples except for patient 1 whose cancer harbored a germline frameshift mutation in BRCA1 (data not shown) without loss of heterozygosity, suggesting at least partial HR proficiency." (PMID 37491309, 2023). "The combinational approach of PARP and ATR inhibition to enhance response to PARP inhibitors could expand the utility of PARP inhibitors to cancer patients without BRCA1/2 mutations." (PMID 36794257, 2023). "In this case, dCas9:TET1 increased BRCA1 expression and inhibited the proliferation of a cancer cell line, highlighting the therapeutic potential of epigenome editing to reduce hypermethylation in promoters of tumor suppressor genes, which is one of the hallmarks of cancer." (PMID 36980849, 2023). "Therefore, the identification of TRIP12-deficient tumors and the development of TRIP12 inhibitors may allow the use of PARP inhibitors in the treatment of BRCA1 proficient cancers." (PMID 38201233, 2023). "In addition to cancer-type-specific thresholds that reduce the number of unexplained cases, we demonstrated the importance of including the promoter methylation status of BRCA1 and RAD51C in order to evaluate the fraction of HRD cases that are explained by known causes." (PMID 35783256, 2022). "Additionally, the BECN1 allelic loss is confounded by its location adjacent to BRCA1 on human chromosome 17q21, raising the possibility that loss of BECN1 in human cancers may be associated with the loss of BRCA1 in human breast and ovarian cancers." (PMID 36528652, 2022). "The type of cancer developed in each DH patient was consistent with the independently inherited condition, and the clinical outcome was no worse than in patients with single BRCA1 mutations." (PMID 36232793, 2022). "This may suggest a dependence for BRCA1-type HRD cancers on PTEN inactivation." (PMID 35159019, 2022). "BRCA1/2-related mutations and cancers should not be considered and treated as a female prerogative." (PMID 35303741, 2022). "Furthermore, as a BRCA1/2-PV is transferred in an autosomal dominant manner, many BRCA1/2-PV carriers have experienced cancer-related morbidity and mortality in their families which can also influence cancer worry." (PMID 34997316, 2022).
cancer (continued). "Two further retrospective analyses found an association between BRCA1/2 status and higher risk of unfavourable histology, disease recurrence and cancer specific-survival (CSS) with a difference of 8.6 years versus 15.7 years between BRCA1/2 pathogenic variant carriers and non-carriers." (PMID 33486571, 2022). "The reduced level of PTEN has been associated with enhanced cancer sensitivity to mTOR inhibitors and could be a potential target for CRISPR/Cas9-mediated gene editing in BC.Patients with defective BRCA1/2 genes have poor DNA repair capacity and are more susceptible to developing BC." (PMID 35879772, 2022). "Our evaluation posed evidences for the pathogenicity significance of the investigated VUS: 1) association of the BRCA1 variant to cancer-affected members of the family; 2) absence of another high-risk mutation; 3) multiple indirect evidences derived from gene and protein structural analysis." (PMID 36741700, 2022). "Based on patterns over time, BRCA1/2-PV carriers could be classified into three groups: persistently low cancer worry (56%), persistently high cancer worry (6%), and fluctuating, mostly declining, cancer worry (37%)." (PMID 34997316, 2022). "However, BRCA1 deficiency is not always associated with BRCAness, as BRCA1 alterations in non-BRCAness cancer seem neither related to tumor pathogens nor therapeutically actionable." (PMID 35327946, 2022). "Given that mouse strains are frequently used in designing and testing preclinical cancer treatment models, we sought to identify Wwox binding regions in murine Brca1 and associated proteins, to define molecular details of its role in DSB repair, in cooperation with Brca1." (PMID 35409089, 2022). "Importantly, cancer risks differ between BRCA1 and BRCA2 PVs as well as by sex." (PMID 36497436, 2022). "However, pan-cancer analysis revealed that uLMS shows characteristic alterations in BRCA1/2." (PMID 35267488, 2022). "The ESMO clinical practice guidelines for PCa recommend early PSA testing in BRCA1/2 carriers >40 years, and germline testing for BRCA2 and other DDR genes associated with cancer predisposition syndromes in men with a family history of cancer, and in all patients with metastatic prostate cancer." (PMID 35740437, 2022). "All these data demonstrate that Brca1 deficiency creates a tumor-permissive environment in mammary tissues through activation of the S100A9-CXCL12 axis, which renders cancer cells insensitive to ICB, and the inhibition of S100A9-CXCL12 signaling could sensitize the cancers to ICB." (PMID 35304461, 2022). "Furthermore, despite the severe impact on fork structure and chromosomal stability, depletion of ZKSCAN3 did not affect the short-term survival of BRCA1-proficient or BRCA1-deficient cells after treatment with cancer drugs hydroxyurea, PARPi, or cisplatin." (PMID 35779634, 2022). "BRCA1/2-PV carriers may be prone to high levels of cancer worry." (PMID 34997316, 2022). "Combined the finding that 83.5% of HGSOC in our study were satisfied/highly satisfied with having reflex BRCA1/2 tumour genetic testing completed as part of their cancer care, available data suggest gaps in knowledge about tumour genetic testing may be of minimal concern for cancer patients." (PMID 35418215, 2022). "Despite ensuring that all patients had tumour results disclosed by their gynecologic oncologist, many could not accurately recall their results; nevertheless, most participants were satisfied with having reflex BRCA1/2 tumour genetic testing completed as part of their cancer care." (PMID 35418215, 2022). "Taken together, these findings suggest that DCAF8L1 could promote cancer cell proliferation and regulate mammary stem/progenitor cell development and differentiation, probably through a mechanism dependent on its negative regulation of BRCA1 protein." (PMID 35280675, 2022). "Not every BRCA1/2 carrier has the same risk of developing cancers; some may never develop cancer throughout their lives." (PMID 35378767, 2022).
cancer (continued). "Finally, patients with BRCA1/2 mutations without cancer should also receive early and regular cancer screening, and prophylactic measures." (PMID 35205313, 2022). "Intriguingly, pathological features contributed more than family cancer history to the ability of DrABC to predict GPVs in BRCA1/2 and any CPGs, which might contribute to the superior performance of DrABC and the reconstructed BOADICEA model than the other previous models." (PMID 35209950, 2022). "Therefore, the treatment of BRCA1/2-deficient cells with PARP inhibitors blocks all three DNA damage repair pathways, leading to the induction of cell death, and these inhibitors have been used as cancer therapeutic strategies." (PMID 35978820, 2022). "As cancer cells often characterized by abnormalities in the DNA repair mechanism, drug development based on synthetic lethality aimed at other remaining DNA repair mechanisms, for example, poly (ADP‐ribose) polymerase inhibitors for treating BRCA1/2‐mutated ovarian cancers, is clinically prominent." (PMID 35000298, 2022). "Additionally, some cancers that do not have actual mutations in BRCA1/2 have high levels of a quality known as “BRCAness”, which indicates their similarity to cancers with mutations in these genes." (PMID 35158750, 2022). "Thus far, three PARP inhibitors, Olaparib, Rucaparib, and Niraparib, have been approved by FDA for treatment of breast and ovarian cancers in patients with mutations in BRCA1 and BRCA2, which are key mediators of HR repair, providing the first anti-cancer therapy based on synthetic lethality." (PMID 35270034, 2022). "Interestingly, database (ClinVar/MedGen) and literature reports suggest that human individuals with a hereditary predisposition for BRCA1/2- and PALB2-associated cancers carry germline point mutations of predominantly hydrophobic residues in the human RAD50 beta-sheet motif." (PMID 35501303, 2022). "Since the BRCA1 and BRCA2 proteins are also involved in the radiation-induced deoxyribonucleic acid (DNA) damage repair and signalling pathway, BRCA1+/− and BRCA2+/− carriers are considered to be at high risk of IR-induced cancer, notably through chest CT scan exams." (PMID 35301607, 2022). "BRCA1 was associated with mothers’ lifespan (HR = 1.64, P = 5.35 × 10−11); 139 of 190 BRCA2 PTVs and 73 of 98 BRCA1 PTVs identified in our study had previously been reported as pathogenic or likely pathogenic in Clinvar13 for heritable breast and ovarian cancer syndrome or related cancers." (PMID 37117740, 2022). "Unlike other tumour genetic tests where PV may be unlikely to confer a hereditary cancer risk, additional germline testing is required when a BRCA1/2 PV is identified via tumour genetic testing." (PMID 35418215, 2022). "Among high-penetrance cancer-predisposing genes, pathogenic variants of BRCA1 and BRCA2 are the most frequent germline alterations found at tumour testing and represent the most common incidental germline finding in unselected populations of cancer-affected individuals." (PMID 35463374, 2022). "Both BRCA1 mutation carriers and 2 mutation carriers could significantly benefit from PARPi regardless of cancer types and therapeutic lines." (PMID 35267543, 2022). "With the development of PARP inhibitors for treatment of cancer patients with an altered BRCA1 or BRCA2 gene, there is an urgent need to ensure that there are appropriate strategies for identifying mutation carriers whilst balancing the increased demand for and cost of cancer genetics services." (PMID 35143328, 2022).
cancer (continued). "The International Cancer of the Pancreas Screening Consortium indicates the screening for PDAC onset in patients with Peutz–Jeghers syndrome, with presence of STK11 mutation; with presence of a CDKN2A, BRCA1/2, or MMR mutation and with a first-degree relative affected with PDAC." (PMID 35205366, 2022). "However, a report also indicated that the elevated TIL abundance is only observed in BRCA1-deficient cancers that carry PTEN mutations but not with BRCA1-deficient cancers expressing WT PTEN20." (PMID 35304461, 2022). "Interestingly, certain types of cancer, such as Ewing’s sarcoma, do not harbor mutations in BRCA1 or BRCA2, but they still are sensitive to PARP inhibitors." (PMID 36613695, 2022). "This is the largest series of BRCA1/2 testing in HGSC (tumor‐only and paired cohorts), reported to date, and our data show that an effectively designed and validated population‐based tumor testing program can be used to determine both treatment eligibility and hereditary cancer risk." (PMID 33030818, 2021). "In the context of BRCA1- and BRCA2-derived cancers, other genes involved in high-volume DNA repair, or those key in other critical pathways whose functionality is required for cell survival and proliferation, are potential contenders for BRCA1/2 synthetic lethal partners." (PMID 34070674, 2021). "Interestingly, although the TNBC cell line HCC-1937 carries a BRCA1 mutation, it was the least sensitive cell line to olaparib among all cell lines tested, suggesting that factors other than BRCA mutations affect cancer cell sensitivity to olaparib, as also shown by other researchers." (PMID 34504648, 2021). "However, because there is a lack of reliable clinical data to confirm PARPis are suitable for treating all types of cancer, patients should have genetic testing for defects in BRCA1/2 and other genes related to homologous recombination deficiency, before PARPis are safely applied." (PMID 33705352, 2021). "As both low levels of BRCA1 and BRCA1 methylation are very common to BLBC38, and our data demonstrate elevated cyclin E1 in the BRCA1 methylated BLBC, a rational ongoing area of investigation is CDK2 inhibition to sensitize BRCA1 methylated or deficient cancers to PARP inhibitors." (PMID 34465787, 2021). "Since BRCA1/2 genetic testing could decrease mortality from breast, prostate, gynecological and some other cancers, and help inform therapy, there is a need to develop or adjust tools to enable targeted treatment and optimal care for all cancer patients." (PMID 34660253, 2021). "In our study, we could not only show that the BRCA1 mutant cell line UWB1.289 displayed a higher PAFR expression than the rest of the epithelial OC cells but also that siRNA knockdown of PAFR in this cell line significantly decreased cancer cell proliferation." (PMID 34571986, 2021). "Since nowadays detailed genetic determination experiments involving noncancer tissue types are not used in routine cancer diagnostics, further such studies are required to reveal the frequency of de novo BRCA1/2 mutations and their contribution to carcinogenesis." (PMID 34068254, 2021). "The hybrid ligands were screened for their inhibitory effects on the viability of six different cancer cell lines, comprising two luminal (ZR75-1, MCF-7), one HER2+ (MDA-MB-453), and three TNBC lines without (MDA-MB-468) and with (HCC-1937, MDA-MD-436) pathogenic BRCA1 mutations." (PMID 34356606, 2021). "Thus, abnormally high replication rates caused by β-catenin accumulation in BRCA2-deficient cells are likely to represent a major source of DNA damage and an important contributing factor to the synergistic effect of oncogene activation and BRCA1/2 abrogation on suppressing cancer cell viability." (PMID 34389725, 2021).